LDHA (lactate dehydrogenase A)
Diseases named in the same sentence as LDHA in open-access papers (continued):
Sharing a sentence is not in itself a finding about the gene and the disease.
lymphoma (26 papers, 2012 to 2025). A malignant (clonal) proliferation of B- lymphocytes or T- lymphocytes which involves the lymph nodes, bone marrow and/or extranodal sites. "In lymphomas, oncogenic myc activation causes a series of metabolism changes, like enhanced mitochondrial biogenesis, acceleration of mitochondrial glutaminolysis, and up-regulation of LDHA expression to drive glycolytic metabolism." (PMID 31835667, 2019). "In LDHA-dependent lymphoma models, combinatory treatment of NAMPT inhibition and the LDHA inhibitor FX11 induced tumor regression in in vivo xenograft models." (PMID 40390151, 2025). "We also observed that the expression of LDHA and alanine transaminase in lymphoma is sporadically elevated." (PMID 39518046, 2024). "When LDHA expression was reduced by small interfering RNA, the progression of lymphoma growth was inhibited." (PMID 35278714, 2023). "Another study showed the results that inhibiting LDHA correlated with oxidative stress-mediated suppression of tumor progression in certain lymphoma cell lines." (PMID 38136270, 2023). "Upregulation of GLUT-1 and LDHA is consistent with the enrichment of glycolysis gene set and suggested that lymphoma cells, as for most tumors, undergo the Warburg effect." (PMID 34557403, 2021). "In highly glycolytic tumors, such as lymphoma, the combination of an LDHA inhibitor and a NAMPT inhibitor resulted in a synergistic anticancer effect." (PMID 29541451, 2018). "However, contrary to the proposed importance of increased LDHA activity in cancer, LDHA has also been identified as dispensable for tumor growth in lymphoma and brain tumor models." (PMID 30087897, 2018). "Although targeting LDHA with short-hairpin RNAs (shRNAs) diminishes tumor xenograft growth in a number of models, the reduction of LDHA activity in a hypomorphic mutant allele of LDHA did not diminish tumorigenesis in the λ-Myc transgenic model of murine lymphoma." (PMID 23342984, 2013). "Targeting key glycolytic enzymes (e.g., LDHA, ENO2) offers a strategy to remodel the metabolic microenvironment of lymphoma." (PMID 40703518, 2025). "This dual effect of LDHA inhibition–increased oxidative stress and NAD+ depletion– has been shown to also occur in lymphoma, although in this cancer type the increased ROS was found to be the main trigger for cell death, while we found the decreased NAD+/NADH ratio to be more consequential in AML." (PMID 40390151, 2025). "studying, murine fibroblasts and lymphoma cells, our data showed knockdown of AMPKα did not alter LDHA expression." (PMID 38301894, 2024). "Among all genes, lactate dehydrogenase genes (LDHA and LDHB) were observed to be the most highly expressed (among the entire transcriptome), followed by transaminase genes (GOT1, GOT2, GPT, and GPT2) with log2 median expression > 10, both in lymphoma patients and cell lines." (PMID 39518046, 2024). "The inhibitors intended to target metabolic enzymes, such as SLC25A1 (CPT1), MCT1 (MCT-III), LDHA (oxamate), glutamine transporter (MK801), and PDH/α-ketoglutarate (Demvistat), without affecting cell viability in the lymphoma cells or LCL." (PMID 39518046, 2024).
non-small cell lung carcinoma (26 papers, 2013 to 2026). A group of at least three distinct histological types of lung cancer, including non-small cell squamous cell carcinoma, adenocarcinoma, and large cell carcinoma. "LDHA is overexpressed and associated with poor prognosis in non-small cell lung cancer (NSCLC), where LDHA inhibition by oxamate remarkably increased radiosensitivity through ROS accumulation and cellular ATP depletion." (PMID 36407005, 2022). "A study unveiled that circSLC25A16 interacted with miR-488-3p/HIF-1α to activate LDHA by promoting its transcription in non-small-cell lung cancer." (PMID 36518315, 2022). "Several lines of evidence indicate that LDHA overexpresses in multiple types of cancer, including breast, colorectal, and non-small cell lung cancers." (PMID 34575112, 2021). "Aberrant expression of LDHA is a hallmark of multiple cancers, including CRC, HCC, esophageal squamous cell carcinoma (ESCC), squamous head and neck cancer, and non-small cell lung cancer (NSCLC)." (PMID 35006438, 2021). "This study suggests that the high expression of rate-limiting enzymes PKM2 and LDHA promoted glycolysis and induced the formation of cisplatin resistance in non-small cell lung cancer A549 cells." (PMID 34046349, 2021). "Clinical trials have also explored the effects of other glycolysis inhibitors, such as lactate dehydrogenase A inhibitors and pyruvate dehydrogenase kinase inhibitors, which have shown promising anti-tumor activity in various cancer models, including non-small cell lung cancer (NSCLC) and HCC." (PMID 39609317, 2024). "Indeed, miR-200c in bladder cancer and miR-449a in non-small-cell lung cancer cell lines were downregulated, enhancing the LDHA level." (PMID 36518315, 2022). "Importantly, we showed the short hairpin RNA (shRNA)-mediated attenuation of Set7/9 augmented c-Myc, GLUT1, HK2, ALDOA, and LDHA expression in non-small cell lung cancer (NSCLC) cell lines, not only at the transcriptional but also at the protein level." (PMID 34692483, 2021). "In the current study, we evaluated the prognostic value of LDHA expression in non-small cell lung cancer (NSCLC), and tested whether LDHA inhibition might improve radiotherapy efficacy in NSCLC." (PMID 33902615, 2021). "SPP1 with glycolysis genes (GAPDH, ENO1, LDHA, ALDOA, and TPI1) was also expressed in TAMs in non-small cell lung cancer (NSCLC)." (PMID 38347955, 2023). "HIF-1-mediated mRNA upregulation of glucose transporter 1 (GLUT1), lactate dehydrogenase A (LDHA), and pyruvate kinase isoform M2 (PKM2) required NOX4-derived ROS production to promote glycolytic switch in thyroid and in diverse non-small cell lung cancer cell lines." (PMID 35269843, 2022).
osteosarcoma (23 papers, 2017 to 2026). A usually aggressive malignant bone-forming mesenchymal neoplasm, predominantly affecting adolescents and young adults. "In human osteosarcoma cells, LDHA silencing downregulated Hedgehog signaling, and inhibition of Hedgehog signaling suppressed cell migration and invasion." (PMID 42240603, 2026). "miR-323a-3p, for instance, amplifies LDHA expression, thereby augmenting lactate generation and fostering metastatic and invasive capabilities in osteosarcoma." (PMID 39850812, 2024). "ac4C‐modified YTHDC1 mediates m6A methylation of PFKM and LDHA to regulate glucose metabolism and promote progression of osteosarcoma." (PMID 39640362, 2024). "Western blot analysis further confirmed this observation, demonstrating a significant decrease in the protein expression of PDK3 and LDHA in osteosarcoma cells due to the overexpression of miR-34a-5p." (PMID 39850812, 2024). "The qRT-PCR analysis results indicated that the expression levels of both PDK3 and LDHA were significantly downregulated in osteosarcoma cells following the overexpression of miR-34a-5p." (PMID 39850812, 2024). "YTHDC1 recognizes differential m6A sites on PFKM and LDHA RNAs, which promotes osteosarcoma cell growth and regulates glycolysis pathway by increasing PFKM and LDHA mRNA stability in an m6A methylation-dependent manner." (PMID 38233839, 2024). "KDM6B regulates H3K27me3 demethylation in the promoter region of LDHA, thereby promoting LDHA expression and aerobic glycolysis in osteosarcoma cells, and hence facilitating tumor metastasis." (PMID 37197432, 2023). "A previous study showed that miR-323a-3p inhibited the growth of Osteosarcoma (OS) cell by targeting LDHA and suppressed the glycolysis of OS." (PMID 31989041, 2019). "A study showed that 2-Deoxy-D-glucose (2-DG) could reduce osteosarcoma growth by inhibiting HK and lactate dehydrogenase A (LDHA), which are the key enzymes involved in anaerobic glycolysis." (PMID 39252946, 2024). "Furthermore, increased expression of LDHA was also observed in an osteosarcoma cancer stem cell-like line 3AB-OS, which showed stronger glycolytic metabolism than the parental MG63 cells." (PMID 27911865, 2017). "Suppressing the expression of LDHA and PDK3 in vivo can disrupt the metabolic pathways of osteosarcoma cells, thereby inhibiting their proliferation and invasiveness." (PMID 39850812, 2024). "Expression profiles of C1QTNF1-AS1, miR-34a-5p, LDHA, and PDK3 in osteosarcoma cells were analyzed using RT-PCR and western blot analyses, revealing their intricate relationships." (PMID 39850812, 2024). "On the metabolic side, osteosarcoma cells typically exhibit glycolysis-biased pyruvate metabolism through PKM2, LDHA, and lactate transporters, processes that not only support proliferation but also remodel the tumor microenvironment and impair immune function." (PMID 41346635, 2025). "The restoration or enhancement of miR-34a-5p function can effectively inhibit the proliferation and invasiveness of osteosarcoma cells, and by modulating the expression of enzymes such as LDHA and PDK3, the metabolic profile of osteosarcoma cells can be altered." (PMID 39850812, 2024). "Therefore, our findings suggest that NAT10 serves as an effective and novel therapeutic target for osteosarcoma through YTHDC1-mediated m6A modification, which can impact the translation efficiency of LDHA and PFKM." (PMID 38233839, 2024). "Our results highlighted that histone demethylase KDM6B played an oncogenic role in the progression of osteosarcoma, KDM6B-mediated H3K27me3 demethylation promotes oncogenic LDHA expression, thereby facilitating OS cell migration in vitro and lung metastasis in vivo." (PMID 33664867, 2021). "A great deal of overlap between LDHA and MB positive samples was seen in malignant tumors apart from lung Squamous cell carcinoma, adenocarcinoma endometrium, cervical squamous cell carcinoma, osteosarcoma of the femur where LDHA immunostaining was positive while MB was negative." (PMID 33996536, 2021).
nasopharyngeal carcinoma (21 papers, 2016 to 2026). A carcinoma arising from the nasopharyngeal epithelium. "Inhibition of LDHA by oxamate reportedly induced G2/M arrest/apoptosis and attenuated in vivo tumor growth of nasopharyngeal carcinoma, suggesting a mechanism by which oxamate acts on tumor cells." (PMID 38033489, 2023). "Additionally, LDHA inhibition has resulted in cell cycle inhibition and apoptosis in nasopharyngeal carcinoma." (PMID 36678382, 2022). "In nasopharyngeal carcinoma, JMJD2A was predicted to boost the Warburg effect through LDHA activation, and fuel tumorigenesis and progression ultimately." (PMID 33777804, 2021). "In patients with nasopharyngeal carcinoma (NPC), the JMJD2A level was reported to be positively correlated with the LDHA expression, further demonstrating the JMJD2A-regulated LDHA expression at the level of transcription by the combination with the LDHA promoter region." (PMID 36518315, 2022). "In nasopharyngeal carcinoma (NPC), JMJD2A promotes warburg effect by transactivating LDHA expression." (PMID 31146503, 2019).
renal cell carcinoma (21 papers, 2010 to 2025). "LDHA inhibition results in increased apoptosis via ROS production in cell with fumarate hydratase deficiency and was viewed as a therapeutic strategy for the treatment of hereditary leiomyomatosis and renal cell cancer." (PMID 31835667, 2019). "Elevated LDHA enzyme activity is conducive to promoting glycolysis and proliferation in renal cell carcinoma cells." (PMID 38764020, 2024). "In renal cell carcinoma, LDHA promotes metastasis by stimulating epithelial-mesenchymal transformation, which can be inhibited by LDHA inhibitors." (PMID 37728418, 2023). "Meanwhile, studies have applied LDHA inhibitors to the treatment of renal cell carcinoma and summarized the basic mechanism of treatment by observing the clinical indicators of the object." (PMID 34604067, 2021). "LDHA has been reported to promote metastasis by facilitating EMT in renal cell carcinoma (RCC), thus suggesting that LDHA may be a promising target for RCC therapy." (PMID 40593465, 2025). "In renal cell carcinoma, LDHA knockdown promoted cell apoptosis and inhibited cell migration." (PMID 39582531, 2024). "A study of renal cell carcinoma showed significant reductions in CD8+ T cell infiltration and granzyme B and perforin levels in tumor tissues with high expression of GLUT-1 and LDHA." (PMID 39408814, 2024).
breast tumor (16 papers, 2015 to 2025). "Increased mitochondrial respiration in breast tumor cells after lactate dehydrogenase A (LDHA) inhibition suggests that cancer cells retain the ability to oxidize glucose through oxidative phosphorylation (OXPHOS) in their mitochondria." (PMID 36902385, 2023). "LDHA-induced glycolysis energy metabolism was suppressed by miR-30a-5p, thus breast tumor growth and metastasis were blocked." (PMID 36109751, 2022). "Our data indicate that POU1F1 induces a metabolic reprogramming through LDHA regulation in human breast tumor cells, modifying the phenotype of both cancer cells and fibroblasts to promote cancer progression." (PMID 33714987, 2021). "Furthermore, we detected the sequence alterations of LDHA mRNA in breast tumor tissues obtained from AI-sensitive and AI-resistant patients using qRT-PCR." (PMID 36418319, 2022). "The downstream genes of lactate catabolic pathways, LDHA and LDHB, also showed potential inverse correlations with BACH1 expression in breast tumors." (PMID 35406740, 2022). "We corroborated these findings by analyzing 49 primary and treatment-naïve breast tumor samples, where we observed a strong inverse relationship between the expression of glycolysis markers (GLUT1 and LDHA) and stromal infiltration of CD3+ and CD8+ T-cells." (PMID 36505421, 2022). "Finally, in primary cultures of human breast tumors, we studied the effect of both POU1F1 and LDHA on fibroblast activation." (PMID 33714987, 2021). "In fact, bioinformatic search of human breast cancer tumors and normal breast samples (GSE22820) revealed a significant (P < 0.001) increase of LDHA mRNA expression in human breast tumors as compared with normal mammary tissue." (PMID 33714987, 2021). "Besides, the expression of LDHA mRNA and LDHA protein was notably promoted in breast tumor tissues compared with that in non-cancer tissues." (PMID 36109751, 2022).
triple-negative breast carcinoma (16 papers, 2017 to 2026). An invasive breast carcinoma which is negative for expression of estrogen receptor (ER), progesterone receptor (PR), and human epidermal growth factor receptor 2 (HER2). "According to further refined distinct subtypes, the distribution of LDHA and FASN expression showed an inverse correlation, with LDHA H-scores increasing from LumA to triple-negative breast cancer (TNBC) and, conversely, with FASN H-scores decreasing from LumA to TNBC." (PMID 32899149, 2020). "In triple-negative breast cancer (TNBC), knockdown of YBX1 inhibited the expression of glycolytic genes (ENO1, SLC2A6, LDHA, PFKP, PGAM1, and GPI) and downregulated the expression of EMT-related genes and tumor migration and invasion." (PMID 41507134, 2026). "In triple negative breast cancer cell lines, LINC01605 knockdown prevented tumor formation and migration in vivo by inhibiting aerobic glycolysis via lactate dehydrogenase A." (PMID 39167430, 2024). "The triple-negative breast cancer cell line, MDA MB231, was found to express NAPRT, to have low levels of QPRT, and to primarily rely on LDHA activity for its resistance to FK866." (PMID 29541451, 2018). "For example, in triple-negative breast cancer (TNBC), it was found that LRPPRC could bind to the m6A-modified mRNA of lactate dehydrogenase A (LDHA)." (PMID 40555877, 2025).
neuroblastoma (14 papers, 2015 to 2025). Neuroblastoma (NB) is the most common solid, extracranial childhood tumor. "YY1 enhanced the aerobic glycolysis and proliferation of neuroblastoma cell via increasing Lactate dehydrogenase A (LDHA) expression by binding to the promoter of LDHA." (PMID 38410123, 2024). "Nevertheless, both studies showed that LDHA is required for neuroblastoma cell growth and tumorigenicity." (PMID 36077650, 2022). "LDHA and PRDX4 were described as overexpressed in high-risk neuroblastomas independently of other markers." (PMID 25869207, 2015). "Having identified MYCN positively correlated genes, we then tested some of them, e.g., PMKs and LDHA, investigating whether they were co-localised in sEV using the doxycycline-inducible neuroblastoma cell line." (PMID 41440947, 2025). "N-MYC amplified neuroblastoma cells are addicted to LDHA, which converts pyruvate to lactate." (PMID 33251216, 2020). "Knockdown of LDHA completely inhibits tumorigenesis in vivo and targeting LDHA could be a promising approach in treating neuroblastoma patients with N-MYC amplification." (PMID 33251216, 2020). "YY1 directly bound to the promoter LDHA, and overexpression of LDHA reverses the inhibitory effect of sh-YY1 on aerobic glycolysis and proliferation of neuroblastoma cells, indicating that YY1 induces aerobic glycolysis and proliferation." (PMID 37081988, 2023). "Both MYCN and hypoxia-inducible factor 1α (HIF-1α) are required for sustaining the aerobic glycolysis phenotype in neuroblastoma cells by transcriptional upregulation of glycolytic enzymes, including hexokinase 2 (HK2) and lactate dehydrogenase A (LDHA)." (PMID 36077650, 2022). "While complementary roles of LDHA and LDHB in brain tumor development have been reported in a neuroblastoma model, double LDHA/B KO in GB stem‐like cells induced a substantial decrease in tumor development via lactate production and consumption impairment." (PMID 36278433, 2022). "Studies have found that the expression level of LDHA in neuroblastomas is not correlated with glycolytic activity." (PMID 39289349, 2024). "Similarly, high levels of N-MYC in N-MYC amplified neuroblastoma cells override HIF1α inhibition of cell cycle progression under hypoxia and cooperates with HIF1α to promote the expression of phosphoglycerate kinase 1 (PGK1), HK2, and LDHA." (PMID 33251216, 2020).